RUNX2 (RUNX family transcription factor 2)
Diseases named in the same sentence as RUNX2 in open-access papers (continued):
Sharing a sentence is not in itself a finding about the gene and the disease.
pancreatic cancer (continued). "Despite the relatively low efficiency of Runx2 silencing in the tested cell lines, there was a significant change in the expression of several target genes such as SPARC and MMP1 in IPSCs and Panc-1 pancreatic cancer cells." (PMID 17876328, 2007). "Coculture of both cell lines without a direct cell-to-cell contact led to increased Runx2 expression in pancreatic cancer cells." (PMID 17876328, 2007). "The reason why the potential tumour suppressor Runx2 is overexpressed in some pancreatic cancer tissues is currently not known, and requires further studies." (PMID 17876328, 2007). "In addition, we examined the hub genes KIT, CDKN1B, RUNX2, and BCL2L11, which may act in pancreatic cancer, and confirmed that the expression of KIT, CDKN1B, RUNX2, and BCL2L11 is indeed affected by miR-221-3p." (PMID 32943991, 2020). "Thus, miR-221-3p may affect the incidence and development of pancreatic cancer by affecting KIT, CDKN1B, RUNX2, and BCL2L11 expression." (PMID 32943991, 2020). "Since, among RUNX family proteins, RUNX2 strongly stimulates VEGF-dependent angiogenesis, RUNX2 might be an attractive molecular target for therapies, which seek to repress malignant progression of solid tumors such as pancreatic cancer." (PMID 29558908, 2018). "Therefore, the observed low-to-absent SPARC expression levels in some pancreatic cancer cells in vivo might be due to suppressive effects of Runx2." (PMID 17876328, 2007).
craniosynostosis (31 papers, 2010 to 2026). Craniosynostosis is defined as the premature fusion of one or more cranial sutures leading to secondary distortion of skull shape resulting in skull deformities with a variable presentation. "Gain-of-function mutation in RUNX family transcription factor 2 (RUNX2) is also responsible for craniosynostosis." (PMID 35451466, 2022). "In contrast, the major causative factors in craniosynostosis (CS), which is characterized by early suture closure and associated skull malformation and craniofacial deformity, are closely associated with the RUNX2 regulation mechanism." (PMID 32788656, 2020). "In contrast, gain-of-function mutations in FGFRs, which are known upstream stimulating signals of RUNX2 activity, cause craniosynostosis (CS) characterized by premature suture obliteration." (PMID 32788656, 2020). "These polygenic mouse models reinforce, in-vivo, that the combination of activation of the IGF1 pathway and disinhibition of the RUNX2 pathway leads to an increased risk of developing craniosynostosis and serves as a model of human SSC." (PMID 31442251, 2019). "Support for this mechanism comes from premature activation of Runx2 in embryonic day (E) 9.5 mice, as well as from the deletion of one allele of Twist1 both of which result in enhanced osteogenesis and craniosynostosis." (PMID 29311969, 2017). "Through promoter analyses, we have recently identified a new direct transcriptional target of Runx2, Nell-1, a craniosynostosis (CS)–associated molecule with potent osteogenic properties." (PMID 20939017, 2011). "Taken together, these data suggest that increased expression of RUNX2 is associated with craniosynostosis." (PMID 20683987, 2010). "Of these, one pair of cousins, each with metopic craniosynostosis, share a heterozygous ∼1 Mb duplication of 6p21 that encompasses RUNX2 and is likely pathogenic." (PMID 20683987, 2010). "Interestingly, genes that likely induce RUNX2 or SP7 expression tend to cause craniosynostosis through gain-of-function mutations or whole gene duplications, such as MSX2101,102, LRP585, SOX11103, IHH104, and RUNX2 itself." (PMID 40087503, 2025). "Contrastingly, increased RUNX2 dosage is a known (but rare) cause of craniosynostosis." (PMID 38760592, 2024). "Moreover, mouse experiments have demonstrated a close association between craniosynostosis and the regulatory mechanism of Runx2." (PMID 37947627, 2023). "Moreover, RUNX2 is also responsible for regulating expression of genes that, when deregulated, cause craniosynostosis like NEL-like 1 (NELL1)." (PMID 34946295, 2021). "Mutations in TWIST1 cause Saethre-Chotzen syndrome, a hereditary form of craniosynostosis, however, we have shown that disinhibition of RUNX2 caused by mutations in the highly conserved TWIST1 twist-box domain is associated with non-syndromic unilateral coronal and sagittal craniosynostosis." (PMID 31442251, 2019). "We screened the RUNX2 coding sequence, intron–exon boundaries and 2 kb of sequence upstream of the start codon in all 186 individuals in an attempt to identify point mutations as a cause of single-suture craniosynostosis." (PMID 20683987, 2010). "Thus, we conclude that much larger studies will be required to confirm whether the RUNX2 11A variant is indeed associated with susceptibility to non‐syndromic craniosynostosis, and if so to confirm the effect size." (PMID 38760592, 2024). "Furthermore, the aberrant upregulation of fibroblast growth factor receptors (FGFRs) is implicated in the pathophysiology of craniosynostosis through Runx2, having as clinical manifestations the premature fusion of sutures, the concomitant deformation of the skull, and facial hypoplasia." (PMID 38791330, 2024).
craniosynostosis (continued). "Importantly, gain-of function coding variants in RUNX2 were reported in patients with midline craniosynostosis and the RUNX2 p.Ala84-Ala89del variant was reported to be significantly enriched in sagittal NCS, implicating overexpression of this gene in the etiology of craniosynsotosis." (PMID 37973980, 2023). "To this end, we have analysed the expression of the different RUNX2 transcript variants in mesenchymal stromal cells isolated from calvarial sutures (CMSC) isolated from unfused suture tissues obtained as surgical waste from surgery of nonsyndromic craniosynostosis (NCS) patients." (PMID 34716352, 2021). "Similarly, duplication of RUNX2 causes syndromic metopic craniosynostosis in humans." (PMID 27606499, 2016). "Given that the genes near many of the loci identified in our pleiotropy-informed GWAS are directly or indirectly related to RUNX2 or SP7, it is possible that together they can predict a considerable proportion of craniosynostosis risk." (PMID 40087503, 2025). "Given the close link between many of the identified loci and the master regulators of suture ossification, RUNX2 and SP7, it is plausible that collectively our loci comprise a polygenic background predictive of craniosynostosis risk and severity." (PMID 40087503, 2025). "PC1 affects the expression of Runx2 and osteocalcin in craniosynostosis in vitro, whereas the functional inhibition of PC1 in primary cranial suture cells increases proliferation and migration and activates the Akt/mTORC2 pathway." (PMID 38791330, 2024). "While our functional studies focused on genes uniquely associated with variation in skull BMD, there are plenty of genes implicated in craniosynostosis (e.g., EN1, RUNX2, SOX6, BMP2, JAG1, LRP5, IDUA30,44,47,48) across the whole set of identified BMD loci." (PMID 37402774, 2023). "ZBP1 depletion inhibits the expression of RUNX2 and AXIN2, both genes associated with craniosynostosis." (PMID 35627201, 2022). "Studies of Runx2 mutants have further supported this premature osteogenic differentiation of the suture mesenchyme in craniosynostosis." (PMID 35451466, 2022). "NR2F2 also regulates Runx2, which has been reported to be overexpressed in some types of craniosynostosis, and has a function in the retinoic acid signaling pathway regulation, which is key in the development of CDH." (PMID 34900871, 2021). "Several interesting examples of CNVs resulting in craniosynostosis include IHH regulatory mutations, RUNX2 duplications, and MSX2 duplications." (PMID 29845577, 2018). "The expression of Nell‐1 is tightly regulated by Runx2, a vital mechanistic convergence point for the development of craniosynostosis." (PMID 28470873, 2017). "Given that RUNX2 is required as a master switch for osteoblast differentiation and interacts with TWIST1, mutations in which also cause craniosynostosis, we conclude that the duplication in this family is pathogenic, albeit with reduced penetrance." (PMID 20683987, 2010). "In addition, in skeletal development and the pathogenesis of craniosynostosis, the reciprocal regulation of RUNX2 and FGF signaling plays an important role." (PMID 35455561, 2022). "Previous studies demonstrated that early onset of RUNX2 expression leads to craniosynostosis." (PMID 33656806, 2021). "While our data suggest that dysregulation of the TWIST1/RUNX2 and IGF1/Akt pathways may predispose humans to craniosynostosis, further translational research is necessary before the development of clinical utility." (PMID 31442251, 2019). "In this study, we describe compound heterozygous mutant mice with genetically altered expression of Igf1 and Gsk3β and disinhibition of Runx2, that result in a significantly increased rate or severity of craniosynostosis when compared to mice with each genotype in isolation." (PMID 31442251, 2019).
craniosynostosis (continued). "Since Runx2 directly regulated the expression of Fgfr1–3, a positive feedback loop between FGFR signaling and RUNX2 may play an important role in the pathogenesis of craniosynostosis and limb defects caused by gain-of-function mutations in FGFR1–3." (PMID 30202094, 2018). "In contrast, early onset of Runx2 expression that eventually results in an increase of the amount of its mRNA in the cranial mesenchyme accelerates the timing of mineralization of cranial dermal bones in mouse embryos and brings about craniosynostosis characterized by overgrowth of bones." (PMID 24711977, 2013). "Further correlation analysis revealed that circPROSC expression was positively correlated with the expression of osteogenic markers (RUNX2, OPN, and COL1A1), which were significantly elevated in fused cranial suture tissues from craniosynostosis patients." (PMID 41178597, 2026). "CircPROSC promotes craniosynostosis by sponging miR‐6815‐5p, thereby activating WNT3A/β‐catenin signaling and enhancing RUNX2‐mediated osteogenesis." (PMID 41178597, 2026). "This work demonstrates for the first time that PC1 regulates RUNX2 activation and osteocalcin gene expression, through an extracellular signal–regulated kinase (ERK)–dependent manner, in a human craniosynostosis cell model." (PMID 33656806, 2021). "In this scenario, our findings indicate that PC1 promotes craniosynostosis, positively regulating ERK, RUNX2 activation and, in turn, cranial suture cell differentiation." (PMID 33656806, 2021). "Copy number variations have been found in cranial suture samples, and RUNX2 has been correlated with the occurrence of syndromic and non‐syndromic craniosynostosis." (PMID 33656806, 2021). "We have previously demonstrated that RUNX2 expression, and particularly the P1-isoform group, are overexpressed in the osteogenic precursor cells (CMSC) isolated from prematurely fused sutures of nonsyndromic craniosynostosis patients." (PMID 34716352, 2021). "We have shown earlier how Gli3Xt−J/Xt−J mice, which produce no functional GLI3 protein, can be used as a model to study craniosynostosis and suture biogenesis, and by genetically reducing the dosage of Runx2 the calvarial phenotype can be rescued." (PMID 29311969, 2017). "This frequency is much greater than any other genotype causing syndromic midline craniosynostosis (e.g., TGFBR1/2, SKI, RUNX2), which are sufficiently rare that their prevalence has not been well-established." (PMID 27606499, 2016). "Besides further supporting the role of ERK in craniosynostosis, our findings pose that ERK acts as a downstream effector of PC1 to activate RUNX2 and subsequently induce osteoblast differentiation in cranial suture cells from trigonocephaly and dolichocephaly patients." (PMID 33656806, 2021). "Thus, it is conceivable that this up‐regulation of Nell‐1 may be resulted from the BMP9‐induced up‐regulation of Runx2, suggesting that BMP9 may play a potential role in regulating the patency of cranial sutures and the development of craniosynostosis." (PMID 28470873, 2017). "Lastly, in order to determine whether aberrant regulation of genes known to be involved in the aetiology of craniosynostosis underpinned any of the defects we observed, we examined the expression of Noggin, FGFR1/pFGFR1, FGFR2, Runx2 and Twist1 by immunohistochemistry." (PMID 27756203, 2016).
Osteopenia (30 papers, 2010 to 2025). Osteopenia is a term to define bone density that is not normal but also not as low as osteoporosis. "Although, RUNX2 levels should be kept in an ideal range since both RUNX2-deficient mice and animals with RUNX2 overexpression presented with osteopenia." (PMID 32937821, 2020). "Runx2 heterozygous knockout mice have osteopenia as adults due to low bone turnover caused by diminished osteoblastic function." (PMID 30154422, 2018). "However, overexpression of Runx2 causes negative regulation of osteoblast maturation which eventually leads to osteopenia." (PMID 33476325, 2021). "Likewise, Csnk2bOsx mice displayed osteopenia and specific phenotypes characteristic of RUNX2 partial loss-of-function." (PMID 32385263, 2020). "RUNX2 expression and activity need to be tightly controlled, as overexpression of Runx2 leads to mice that have osteopenia and suffer from multiple fractures." (PMID 38200847, 2023). "Mice with combined Tet1 and Tet2 deficiency exhibited impairment in osteogenic differentiation and osteopenia, due to reduced demethylation of the P2rX7 promoter and thus an accumulation of RUNX2-suppressing miRNAs." (PMID 34064134, 2021). "The specific deletion of exon 8 of Runx2 in osteoblasts decreased bone formation and caused osteopenia in mice, and DDR1 deletion reduced Runx2 activity and decreased vascular calcification." (PMID 33003599, 2020). "Previously, the maturational blockage of osteoblasts and osteopenia have been reported in mice overexpressing Runx2." (PMID 26844285, 2015). "Further, the osteopenia in Sp7 or Runx2 transgenic mice was worsened in Sp7/Runx2 double transgenic mice and the expression of Col1a1 and Bglap2 was reduced." (PMID 22396760, 2012). "The double transgenic mice showed severe osteopenia and suffered from more severe multiple fractures than tg2 or Runx2 single transgenic mice." (PMID 22396760, 2012). "Targeted deletion of Pkd1 in osteoblasts results in osteopenia and abnormalities in Runx2-mediated osteoblast development." (PMID 21151991, 2010). "Additionally, Runx2 heterozygous knockout mice exhibit osteopenia in adulthood due to reduced bone turnover resulting from impaired osteoblastic function." (PMID 39467699, 2024). "Interestingly, overexpression of Runx2 in osteoblasts driven by a Col1a1 promoter results in impaired matrix production and osteopenia with multiple fractures in mice." (PMID 34064134, 2021). "It was reported that Runx2 overexpression transgenic mice exhibited severe osteopenia." (PMID 33476325, 2021). "It has been demonstrated that Runx2 is essential for skeletal development, however, due to negative regulation of osteoblast maturation, overexpression of Runx2 in cells of the osteoblastic lineage leads to osteopenia." (PMID 33476325, 2021). "Transgenic mice overexpressing Runx2 in osteoblasts exhibited symptoms of osteopenia." (PMID 31419079, 2019). "The depletion of Tet1 and Tet2 may lead to hypermethylation of the P2rX7 promoter to block miR-297a-5p, miR-297b-5p, and miR-297C-5p release, leading to downregulation of Runx2 signaling and osteopenia phenotype." (PMID 29858571, 2018). "Runx2 overexpression leads to osteopenia and multiple fractures, through increased receptor activator of NF-κB ligand (RANKL) expression which in turn could stimulate OCL activity." (PMID 28300755, 2017). "Mutations in Runx2 lead to Cleidocranial dysplasia syndrome, and lack of Runx2 results in complete absence of bone formation, whereas overexpression of Runx2 results in osteopenia and blunted terminal differentiation of osteoblasts and mineralization." (PMID 23846726, 2013). "Salvianolate treatment ameliorate osteopenia and improved bone quality through increasing the Osterix, OPN, Runx2 level and decrease TNF-α, IL-6 level in serum." (PMID 36387862, 2022).
Osteopenia (continued). "Here, the results showed that LA inhibited oxidative stress, suppressed apoptosis and improved osteopenia by promoting the expression of osteogenesis markers, including ALP, COL-I, OCN, BMP-2, RUNX2 and OSX." (PMID 28611356, 2017). "Salvianolate treatment could increase Osterix, OPN, Runx2 level and decrease TNF-α, IL-6 level in serum and IL-1β protein in TNF-α-induced MC3T3-E1 osteoblasts, finally ameliorate osteopenia and improved bone quality." (PMID 36387862, 2022).